BRCA2 (BRCA2 DNA repair associated)
Diseases named in the same sentence as BRCA2 in open-access papers (continued):
Sharing a sentence is not in itself a finding about the gene and the disease.
ovarian carcinoma (continued). "A Hong Kong study of 1,236 patients with high-risk hereditary breast and/or ovarian cancers showed that, among 120 deleterious BRCA mutations, 8 (6.7%) were LGRs involving BRCA1 (5/57, or 8.8%) and BRCA2 (3/63, or 4.8%)." (PMID 35924163, 2022). "Genotyping of 21 mutations in BRCA1, BRCA2, RAD51C, PALB2, and CHEK2 genes was performed for 102 BOT patients, 167 cases of ovarian cancer G1, and 1743 healthy controls." (PMID 35313928, 2022). "The aim of this study was to evaluate the role of MAGEC3 and BRCA2 in epithelial ovarian cancer progression." (PMID 36230652, 2022). "The other two individuals both carried truncated BRCA2 (familial breast/ovarian cancer, MIM 612555)." (PMID 36143288, 2022). "In this study, we measured the levels of BRCA1 and BRCA2 mRNA in ovarian cancers and normal fallopian tubes, the organ from which most ovarian cancers originate." (PMID 35203410, 2022). "While lifetime risk of developing ovarian cancer for women in the general population is about 1.2%, the risk was estimated to be 39–59% and 11–17% for women who carry BRCA1 and BRCA2 mutations, respectively, by age 70–80." (PMID 35625955, 2022). "The lifetime risk of developing ovarian and/or fallopian tube cancer (referred to as ovarian cancer hereafter) has been estimated to be between 44 to 49% for women with a BRCA1 mutation and between 17 to 21% for those with a BRCA2 mutation." (PMID 35668475, 2022). "Like BRCA2, MAGEC3 is an ovarian cancer predisposition gene that has been shown to have prognostic significance in ovarian cancer patients." (PMID 36230652, 2022). "Approximately 5–10% of all BCs have family history of breast or ovarian cancer, and women with germline mutations in breast cancer type 1 (BRCA1) and type 2 (BRCA2) are of greater risk of developing breast or ovarian cancer." (PMID 36140723, 2022). "We found a weak inverse correlation between MAGEC3 and BRCA2 expression in epithelial ovarian cancers." (PMID 36230652, 2022). "Inherited susceptibility to ovarian cancer is found in approximately 15% of patients, the vast majority of which have germline heterozygous mutations in the BRCA1 or BRCA2 genes." (PMID 35203410, 2022). "Of the 240 ovarian cancer patients, 60 carried a BRCA mutation (43 patients (72%) with a BRCA1 mutation and 17 patients (28%) with a BRCA2 mutation)." (PMID 35409996, 2022). "The nomogram based on the BOADICEA (Breast and Ovarian Analysis of Disease Incidence and Carrier Estimation Algorithm) prediction model can be used to predict breast or ovarian cancer risk in individuals with BRCA1 and BRCA2 mutations." (PMID 36203677, 2022). "Monoallelic pathogenic variants in FANCD1/BRCA2, FANCS/BRCA1, FANCJ/BRIP1, FANCM, FANCN/PALB2, and FANCO/RAD51C have been linked to familial breast and ovarian cancer." (PMID 36428697, 2022). "Triple negative breast (TNBC) and ovarian carcinomas (OvCas) with BRCA1 promoter methylation (BRCA1meth) respond more poorly to alkylating agents compared to those bearing mutations in BRCA1 and BRCA2 (BRCAmut)." (PMID 35857626, 2022). "About 10% of ovarian cancer patients were found to be associated with genetic risk and the first known susceptibility genes are BRCA1 and BRCA2." (PMID 36729997, 2022). "Along with defects in BRCA1 and BRCA2, other genes that function in homologous recombination repair (HRR) are mutated in ovarian cancer, albeit at lower frequencies, including RAD51C, RAD51D, BRIP1, PALB2, and ATM." (PMID 35223797, 2022). "The prevalence of ovarian cancer in BRCA1 mutation carriers is 1.5% in <40 years of age and increases up to 10–21% by 50 years of age, while in BRCA2 mutation carriers, the risk is less than 3–5% by 50 years of age." (PMID 35267543, 2022).
ovarian carcinoma (continued). "Common genetic variation (represented by single nucleotide polymorphisms (SNPs)) at loci encoding for functional interactors of BRCA1 and/or BRCA2 modify breast and/or ovarian cancer risk in carriers of germline BRCA1 and/or BRCA2 mutations." (PMID 35053516, 2022). "Despite these limitations, our study has considerable strengths, including the analysis of a large cohort of patients to provide insight into the relationship between MAGEC3 and BRCA2 protein expression in ovarian cancer cases." (PMID 36230652, 2022). "Poly(ADP-ribose) polymerases inhibitor (PARPi) have shown clinical efficacy in ovarian carcinoma, especially in those harboring defects in homologous recombination (HR) repair, including BRCA1 and BRCA2 mutated tumors." (PMID 35406579, 2022). "Specifically, BRCA1 accounts for 81% of breast–ovarian cancer families, while BRCA2 only accounts for 14% of these families." (PMID 35740092, 2022). "Only up to 25% of the cases in which there is a familial aggregation of breast and/or ovarian cancer are explained by germline mutations in the well-known BRCA1 and BRCA2 high-risk genes." (PMID 35595798, 2022). "Ovarian cancer cases expressing BRCA2 with low levels of MAGEC3 fare better than those with normal levels." (PMID 36230652, 2022). "The exons 11 were the largest in both BRCA1 and BRCA2, covering more than half of the gene coding sequence and containing ovarian cancer cluster regions." (PMID 35406410, 2022). "The majority of PVs conferring ovarian cancer risk occur in the BRCA1 or BRCA2 genes (herein: BRCA1/2); however, additional ovarian cancer risk genes have also been identified." (PMID 35418215, 2022). "Current findings suggested implications for the planning of a screening programme for BRCA1 and BRCA2 genes testing in breast and ovarian cancer patients and genetic screening of their relatives." (PMID 35205313, 2022). "The most important risk factor for ovarian cancer is a family history of breast and ovarian cancer, often in association with inherited variants in BRCA1 and BRCA2 as well as in other breast and/or ovarian cancer susceptibility genes." (PMID 35326583, 2022). "Both cases provide further evidence for the gynaecological cancer risk from mosaicism of BRCA1/BRCA2, which has so far only been reported in a single case of BRCA2 mosaicism in a woman with ovarian cancer." (PMID 36068545, 2022). "The prevalence analysis of BRCA1 and BRCA2 LGRs across multiple cancers revealed that BRCA1 LGR more frequently occurred in ovarian cancer (1.31%, 33/2526), and BRCA2 LGR was more commonly seen in cholangiocarcinoma (0.47%, 2/425)." (PMID 36147908, 2022). "The extent to which BRCA1 and BRCA2 mRNA levels are regulated in ovarian cancer has remained poorly understood." (PMID 35203410, 2022). "The risk of ovarian cancer in BRCA1 and BRCA2 mutation patients is 44% and 17%, respectively, whereas the lifetime risk of breast cancer is up to 72% in these patients." (PMID 35180738, 2022). "Recently, we found that pathogenic founder/recurrent germline mutations in 4 genes (BRCA1, BRCA2, RAD51C, PALB2) are responsible for 12.5% of ovarian cancer cases among unselected patients in the Polish population." (PMID 35313928, 2022). "BRCA1 and BRCA2 are the most commonly tested genes in women with epithelial ovarian cancer (EOC) and around 8% of unselected women diagnosed with EOC have a germline pathogenic variant." (PMID 36068545, 2022). "Genetic testing of 1,342 ovarian cancer patients revealed that 176 patients had BRCA gene mutations, including 107 BRCA1 mutations and 67 BRCA2 mutations, and two mutations in both genes, accounting for 13.3% of the comprehensive mutation frequency." (PMID 36685881, 2022).
ovarian carcinoma (continued). "For instance, it is well established that monoallelic mutations in FANCS/BRCA1 and/or FANCD1/BRCA2 are associated with breast and ovarian cancer susceptibility." (PMID 35330396, 2022). "The patient inclusion criteria include positive family history of breast or ovarian cancer or HRD mutations in the BRCA1, BRCA2, PALBB2, or FANC genes." (PMID 35328658, 2022). "We evaluated matched primary and recurrent ovarian cancer from 14 women, 10 BRCA1 and four BRCA2 pathogenic variant carriers." (PMID 36344544, 2022). "Four devices, spanning three therapeutic products, were identified for BRCA1 and BRCA2 for ovarian cancer." (PMID 35689144, 2022). "In ovarian cancer patients, there were 52.94% (9/17) and 75.0% (6/8) of pathogenic variants were distributed in exon 14 of BRCA1 and exon 11 of BRCA2, respectively." (PMID 35918668, 2022). "Having established that BRCA1 and BRCA2 expression was correlated with that of other HR genes in ovarian cancers, we sought to develop a targeted and less costly approach to measure BRCA1/2 mRNA levels in FFPE clinical samples." (PMID 35203410, 2022). "In a retrospective cohort of 5799 families (men/women) from the HBOC group, an increased risk of PC was observed in breast and ovarian cancer patients both carrying BRCA1 and BRCA2 gene mutations." (PMID 35761384, 2022). "Most breast and ovarian cancers are sporadic, however, a germline pathogenic mutation in BRCA1 or BRCA2 genes is carried in approximately 5% of BC and 10–15% of EOC patients." (PMID 36307994, 2022). "For instance, BRCA1 and BRCA2 are partially responsible for breast and ovarian cancers, and their SNVs are widely used for cancer diagnosis." (PMID 35743744, 2022). "Beyond breast and ovarian cancer, prostate and pancreatic cancer also have targetable homologous recombination deficiency (HRD) beyond the well-known BRCA1 and BRCA2 with relevance that exceeds diagnostic purposes." (PMID 35740616, 2022). "One of the predisposing factors for epithelial ovarian cancer (EOC) is germline mutation in tumor suppressor genes, such as BRCA1 and BRCA2 (BRCA1/2)." (PMID 36143252, 2022). "Since the identification of BRCA1 and BRCA2 genes in the 1990s as the landmarks of hereditary breast and ovarian cancer, human beings enter the era of cancer genetic testing." (PMID 36439508, 2022). "Hereditary breast and ovarian cancers result mainly from inherited mutations in HRR genes, when the most common inherited mutations are in BRCA1 or BRCA2 genes." (PMID 36231059, 2022). "This is because in the BRCA2 mutant PEO1 ovarian cancer cells only a barely detection of CCDC6 protein was observed at immunoblot, likely due to an enhanced CCDC6 proteolysis." (PMID 35964058, 2022). "In clinical cohorts of ovarian cancers, we observed that tumors with low FEN1/low BRCA2 co-expression were associated with good PFS (p = 0.038) compared to tumors with high FEN1/high BRCA2 co-expression." (PMID 33919707, 2021). "The aim of the study was to analyze the prevalence and association of recurrent founder germline mutations in BRCA1, BRCA2, RAD51C, PALB2, and CHEK2 genes with ovarian cancer risk among unselected patients in the Polish population." (PMID 33670479, 2021). "The cumulative risk of developing ovarian cancer by age 80 years is 44% for BRCA1 and 17% for BRCA2 carriers." (PMID 33922503, 2021). "Female carriers of BRCA1/BRCA2 variants also have the additional high risk of ovarian cancer, with the cumulative lifetime risk in carriers of BRCA1 being 44% (36–53%), compared to BRCA2, which is 17% (11–25%)." (PMID 34771713, 2021). "This study is the first to characterize constitutional mosaicism down to the single-cell level, and it demonstrates that BRCA2 mosaicism occurring early during embryogenesis can drive tumorigenesis in ovarian cancer." (PMID 34068254, 2021).
ovarian carcinoma (continued). "Approximately 75% of women with hereditary breast and ovarian cancers have germline BRCA1 mutations (gBRCA1), and 10–20% have germline BRCA2 (gBRCA2) mutations." (PMID 33808557, 2021). "A study on hereditary breast cancer/ovarian cancer revealed that the mutations in BRCA1, BRCA2, RAD51, PALB2, and PRIP1 are associated with the ICL repair pathways." (PMID 34712221, 2021). "Some of the genetic risk factors for ovarian cancer include mutations in the tumor suppressor genes BRCA1 and BRCA2." (PMID 33910165, 2021). "Genotyping of 21 mutations in BRCA1, BRCA2, RAD51C, PALB2, and CHEK2 genes was performed for all 2270 ovarian cancer patients and 1743 healthy controls." (PMID 33670479, 2021). "The cancer cluster region for BRCA2 in ovarian cancer is located from c.3249 to c.5681 (RHR = 0.51; 95% CI, 0.44–0.60; P = 6 × 10− 17) and c.6645 to c.7471 (; RHR = 0.57; 95% CI, 0.41–0.80; P = .001)." (PMID 34711195, 2021). "A similar effect was observed when measuring olaparib and cisplatin resistance of BRCA2-mutant PEO1 ovarian cancer cells." (PMID 34871431, 2021). "Herein, for the first time, among Belarussian ovarian cancer patients, we detected BRCA1 c.3756_3759delGTCT, c.68_69delAG, c.1687C > T, and BRCA2 c.658_659delGT mutations." (PMID 33478551, 2021). "For BRCA2, there were 28 of 421 PPCs (6.7%—range 36‐87, median 63 years) slightly older than all BRCA2 ovarian cancers (range 32‐89 years, median 58.0 years)." (PMID 33152107, 2021). "The cumulative lifetime ovarian cancer risk was estimated to be 36.9% (95% CI: 23.4–53.9%) for BRCA1 and 14.9% (95% CI: 7.4–28.5%) for BRCA2 carriers." (PMID 34063308, 2021). "The risk of ovarian cancer increases significantly by the age of 36–39 with BRCA1 mutation carriers and by the age of 44–46 with BRCA2 mutation carriers." (PMID 34828379, 2021). "Amplification or overexpression of the EMSY transcriptional repressor leads to BRCA2 silencing in approximately 20% of high-grade ovarian carcinoma cases." (PMID 34711195, 2021). "We found that a pathogenic mutation in BRCA1, BRCA2, RAD51C or PALB2 was found in 12.51% of unselected cases of ovarian cancer in Poland." (PMID 33670479, 2021). "Accumulated evidence has demonstrated that the expression level of BRCA2 is altered in breast and ovarian cancer, offering a potentially important tool for use in cancer management." (PMID 34573332, 2021). "Among patients with ovarian cancer, the retention rate of BRCA1/2 mutation was 8.3–14.7% (BRCA1: 3.4–9.9%, BRCA2: 4.7–5.3%)." (PMID 32862296, 2021). "Of the 21 study participants with ovarian cancer, 5 had a P/LP variant in BRCA1 (n = 4) and BRCA2 (n = 1) and were diagnosed with high-grade papillary serous ovarian cancer." (PMID 33646313, 2021). "Diverse defects in HR DNA repair genes, such as germline mutations in BRCA1, BRCA2, and PALB2, somatic mutations in BRCA1 and BRCA2, and promoter methylation of BRCA1, have been reported in breast and ovarian cancers." (PMID 34249730, 2021). "The findings support early RRBSO ideally just before the main risk periods for ovarian cancer in BRCA1 aged 35 years (there were two ovarian cancers aged 37.7 and 38.7 years) and BRCA2 aged 45 years." (PMID 33152107, 2021). "These moderate penetrance genes are associated with lower lifetime risks of ovarian cancer than BRCA1 and BRCA2, but still confer significantly increased risk compared to the general population, with lifetime risks ranging from 6 to 15%." (PMID 33926482, 2021). "Secondary epimutations have also been evaluated in breast and ovarian cancer, where people who carry germline BRCA1 and BRCA2 mutations are at high risk of developing this syndrome." (PMID 34638292, 2021).
ovarian carcinoma (continued). "Studies regarding the direct testing of BRCA mutations and variants showed that these mutations marked increase ovarian cancer with SIR values of 139.12 (BRCA1) and 74.93 (BRCA2), whereas the effects in other cancers mostly have SIR values of around 1–2." (PMID 34577828, 2021). "BRCA1 and BRCA2 are involved in almost half of all families containing two or more ovarian cancer cases." (PMID 34207450, 2021). "Several founder mutations in the BRCA1, BRCA2, PALB2, RAD51C, and CHEK2 genes are associated with breast and ovarian cancer." (PMID 33670479, 2021). "Secondary malignancies were excluded, as the primary objective of the study was to reflect the frequency of BRCA1/BRCA2 PSVs in primary ovarian cancer patients." (PMID 34930165, 2021). "In the scenario of Brazilian ovarian cancer patients, for whom BRCA1/BRCA2 mutation frequency is 20%, performing genetic testing and adopting prophylactic measures for family members was considered a cost-effective measure." (PMID 34287479, 2021). "Previous research has shown that the presence of germline or tumor PVs in BRCA1 or BRCA2 predict benefit from such therapies among women with ovarian cancer." (PMID 33926482, 2021). "We therefore tested synthetic lethality in BRCA2-deficient (PEO1) and BRCA2-proficient (PEO4) ovarian cancer cells." (PMID 33674744, 2021). "In Poland, founder mutations in BRCA1, BRCA2, PALB2, CHEK2, and RAD51C have been associated with familial breast and ovarian cancer." (PMID 33670479, 2021). "In ovarian cancer, MMR deficiency is the most common cause of hereditary ovarian cancer after BRCA1 and BRCA2 mutations." (PMID 34207450, 2021). "The risk of developing ovarian cancer varies between 39%-63% and 16.5%-27% in women with pathogenic mutations in the BRCA1 and BRCA2, respectively." (PMID 34547799, 2021). "It should be noted that the incidence of ovarian cancer and the percentage of cases of carrier-induced BRCA1 or BRCA2 mutations are among the highest in the world." (PMID 33478551, 2021). "So far, few studies have been focused on understanding the differences in transcriptome and functional landscapes associated with the disease (breast vs. ovarian cancers), gene (BRCA1 vs. BRCA2), and mutation type (germline vs. somatic)." (PMID 33525353, 2021). "The corresponding ovarian cancer risks were 14% (95% CI, 2% to 24%), 33% (8% to 50%), and 20% (2% to 35%) in carriers of the 185delAG, 5382insC in BRCA1 and 6174delT mutations in BRCA2, respectively." (PMID 34356066, 2021). "As the second most commonly affected gene in hereditary breast and ovarian cancer, BRCA2 especially warrants further study." (PMID 34196900, 2021). "Inhibitors of PARP generate synthetic lethality in BRCA1- and BRCA2-mutant breast/ovarian cancer cells." (PMID 33691794, 2021). "The aim of the study was to analyze the frequency and magnitude of association of 21 recurrent founder germline mutations in BRCA1, BRCA2, PALB2, RAD51C, and CHEK2 genes with ovarian cancer risk among unselected patients in Poland." (PMID 33670479, 2021). "Similar to BRCA2, the median age of ovarian cancer diagnosis was older for women with a PV in BRIP1 (65 years), RAD51C (62 years), or RAD51D (57 years)." (PMID 33926482, 2021). "PV in 10 PDAC patients with multiple primary tumors affected 3 × BRCA1 and 4 × BRCA2 (all had also developed breast and/or ovarian cancer), 1 × PMS2 and 1 × MLH1/MSH6 (both developed colon cancer), and 1 × CDKN2A (diagnosed with melanoma)." (PMID 34503238, 2021). "Pathogenic variants in the BRCA1 or BRCA2 genes are the most common cause of HBOC, and variant carriers have a 5- to 20-fold increased risk of developing breast or ovarian cancer." (PMID 34072979, 2021).